GSDMD (gasdermin D)
Diseases named in the same sentence as GSDMD in open-access papers (continued):
Sharing a sentence is not in itself a finding about the gene and the disease.
alcoholic hepatitis (7 papers, 2021 to 2025). Acute hepatitis resulting from ingestion of alcohol. "Mechanisms and consequences of Gasdermin D (GSDMD) activation in alcoholic hepatitis (AH) are unclear." (PMID 38532477, 2024). "The study has showed that noncanonical CASP11 activation activates GSDMD to cause pyroptosis in alcoholic hepatitis and worsen hepatocellular lytic death." (PMID 35309514, 2022). "Specifically, noncanonical caspase (CASP)‐11‐mediated cleavage of Gasdermin D (GSDMD) has been identified as a key mechanism mediating the progression from chronic ALD to alcoholic hepatitis (AH)." (PMID 41362700, 2025).
alcoholism (7 papers, 2021 to 2025). "Disulfiram (DSF), an FDA-approved medicine for the treatment of alcohol dependence, has recently been identified as an inhibitor of GSDMD, acting via inhibition of GSDMD-N oligomerization." (PMID 40759573, 2025). "Among these, two FDA-approved drugs, disulfiram and diroximel fumarate (DMF), which are used for the treatment of alcohol dependence and relapsing multiple sclerosis, respectively, have been proven to be efficacious GSDMD inhibitors." (PMID 38607004, 2024). "Moreover, disulfiram, an FDA-approved drug for treating alcoholism, has been shown to inhibit GSDMD pore formation by modifying the Cys191 residue of human GSDMD." (PMID 39066985, 2024). "Here, we emphasized the Food and Drug Administration (FDA)-approved alcoholism-averting drug, disulfiram, which was identified as an inhibitor of GSDMD pore formation by covalently modifying human/mouse Cys191/Cys192 in GSDMD and preventing IL-1β release and pyroptosis." (PMID 35655782, 2022). "Disulfiram is a Food and Drug Administration (FDA)-approved anti-alcoholism drug, which is reported as an effective pyroptosis inhibitor by either directly covalently modifying GSDMD or indirectly inhibiting the cleavage of GSDMD via inactivating Nod-like receptor protein 3 inflammasome." (PMID 34858995, 2021). "Disulfiram, a clinically approved agent for alcohol dependence, has been reported to inhibit GSDMD-mediated pore function, whereas the small-molecule compound LDC7559 was initially proposed to block GSDMD-dependent NET release." (PMID 41395250, 2025).
Arthritis (7 papers, 2021 to 2025). Inflammation of a joint. "In this study, we sought to determine the role of GSDMD in arthritis using mice sufficient or insufficient in this protein." (PMID 34784954, 2021). "Although the characterization of GSDMD+ cells in the synovium was outside the scope of this study, we posited that they included macrophages, which populate this tissue in various arthritis disease models and highly express GSDMD." (PMID 34784954, 2021). "In this study, we demonstrate that arthritis in mice with myeloid-specific Pggt1b deficiency is driven by unprenylated GTP-bound small RHO family GTPases, which in turn trigger Pyrin (Mefv) inflammasome activation, GSDMD-dependent macrophage pyroptosis, and IL-1β secretion." (PMID 40883609, 2025). "Since GSDMD deficiency protects mice upon TNF-induced shock, and RA is known to be driven by TNF, it is tempting to speculate that deletion of GSDMD, or other GSDMs, could be protective upon arthritis induction in vivo." (PMID 35455985, 2022).
cerebral infarction (7 papers, 2022 to 2026). An ischemic condition of the brain, producing a persistent focal neurological deficit in the area of distribution of the cerebral arteries. "Our study provides new evidence that i-HPK1 suppresses neutrophil hyperactivation by blocking NF-κB/STAT3/p38-MAPK and GSDMD pathways and neutrophil trafficking into the brain and lungs, ultimately alleviating cerebral infarction and pulmonary injury following AIS." (PMID 40169896, 2025). "Although the levels of Caspase1 and Gasdermin D decreased after cerebral infarction in all three groups, the expression levels of Caspase1 and Gasdermin D were higher in the HAX-1 overexpression group than those in the control group, and the knockout group showed the lowest levels of expression." (PMID 38811533, 2024). "In vivo, combined therapy in the transient middle cerebral artery occlusion mouse model reduced cerebral infarction and improved neurological outcomes, accompanied by NLRP3/GSDMD downregulation and hippocampal neuron preservation." (PMID 40878776, 2026). "Calycosin significantly reduced neurological impairments and brain infarction in a dose-dependent manner, alleviated neuronal damage and decreased the expression of pyroptosis-related markers, including NLRP3, GSDMD, HMGB1, IL-1β, IL-18, and caspase-1." (PMID 40606597, 2025). "Results showed that EA could reduce the score of neurological deficit, reduce the volume of cerebral infarction and improve the degree of nerve cell injury, and inhibit NLRP3, pro-caspase-1, cleaved caspase-1 p20, pro-IL-1β, cleaved IL-1β, and GSDMD protein expression." (PMID 35600074, 2022).
Cirrhosis (7 papers, 2021 to 2025). A chronic disorder of the liver in which liver tissue becomes scarred and is partially replaced by regenerative nodules and fibrotic tissue resulting in loss of liver function. "For example, in clinical studies, patients with cirrhosis have shown elevated levels of circulating GSDMD, IL-1β, and IL-18." (PMID 40667485, 2025). "The protein expression of uncleaved GSDMD in neutrophils isolated from the individuals with cirrhosis was significantly higher than that in the healthy controls with or without LPS incubation." (PMID 39201786, 2024). "Mechanistically, our current findings suggest that the sterile inflammatory milieu in cirrhosis promotes caspase-4-dependent activation of neutrophil-GSDMD, which leads to NETs generation in the thrombus and liver." (PMID 39201786, 2024). "Compared with those in the cirrhosis group, GSDMD-positive cells in the Exo-rBMMSC groups were dramatically decreased (*** p < 0.001)." (PMID 36552767, 2022). "The NLRP3 inflammasome is significantly activated in a CCL4-induced mouse model of cirrhosis, which aggravates hepatocyte death and cirrhosis through the NLRP3/caspase-1/GSDMD classical pyroptosis pathway." (PMID 37370025, 2023). "However, despite the multitudes of studies on GSDMD, no studies on small-molecule drugs targeting GSDMD for the treatment of cirrhosis can be retrieved from PubMed." (PMID 40667485, 2025).
liver cancer (7 papers, 2022 to 2026). An epithelial or non-epithelial malignant neoplasm that arises from the liver. "Our findings also confirmed that YAP1 was positively related to cGAS, STING, and GSDMD in liver cancer tissues." (PMID 40918140, 2025).
Myocardial fibrosis (7 papers, 2022 to 2025). "Astragaloside‐IV alleviated MI‐induced myocardial fibrosis and pathological cardiac remodelling by suppressing ROS/Caspase‐1/GSDMD signalling pathway in mice." (PMID 39929748, 2025). "MI‐induced myocardial fibrosis and cardiac remodelling by inhibiting ROS/Caspase‐1/GSDMD‐NT signalling pathway after MI." (PMID 39929748, 2025). "Meanwhile, myocardial fibrosis was markedly ameliorated, the collagen was decreased through suppressing GSDMD-mediated pyroptosis when PVT1 knockdown." (PMID 35509275, 2022). "In this study, we found that PJ34 in GSDMD KO mice protected cardiac function and reduced myocardial fibrosis in the chronic phase of I/R." (PMID 35783187, 2022). "Meanwhile, Masson's staining showed that the range of myocardial fibrosis in GSDMD KO mice was significantly increased." (PMID 35783187, 2022). "The level of myocardial fibrosis in GSDMD KO mice was significantly increased in I 45 min/R 4 w, while PJ34 could partially reduce the level of fibrosis." (PMID 35783187, 2022). "Moreover, recent research has shown that GSDMD-mediated pyroptosis plays a significant role in the occurrence and development of DN, and AS-IV could alleviate MI-induced myocardial fibrosis and cardiac remodeling by suppressing the ROS/Caspase-1/GSDMD signaling pathway." (PMID 38572426, 2024). "In addition, our experiments turned out that GSDMD KO mice showed a significant decrease in myocardial injury in the acute phase of I/R (45 min/24 h), but, contrary to expectations, decreased cardiac function and increased myocardial fibrosis were observed during the chronic phase (45 min/4 w)." (PMID 35783187, 2022). "In vivo experimental results showed that LGZGD could significantly improve cardiac function, alleviate myocardial fibrosis, reduce the level of inflammatory factors, and inhibit the activation of NLRP3/Caspase-1/GSDMD signaling pathway." (PMID 35615687, 2022).
brain injury (6 papers, 2021 to 2025). Acute and chronic (see also brain INJURIES, CHRONIC) injuries to the brain, including the cerebral hemispheres, CEREBELLUM, and brain STEM. "GSDMD is a key executor of inflammasome-induced pyroptosis, and hyperoxia is known to reduce cell survival and cause cell death in hyperoxia-induced brain injury models." (PMID 37398125, 2023). "Alternatively, studies directed at inhibiting EV formation or cellular uptake will also be important in understanding the mechanisms by which EV GSDMD plays a pivotal role in BPD-associated brain injury." (PMID 33888735, 2021). "To elucidate the mechanism by which CPCGI mitigates microglial pyroptosis following brain trauma, we assessed the expression of key inflammasome‐related proteins, including NLRP3, pro‐caspase‐1, p20 caspase‐1, and GSDMD, using western blot analysis." (PMID 40059065, 2025).
cervical carcinoma (6 papers, 2020 to 2025). A carcinoma arising from either the exocervical squamous epithelium or the endocervical glandular epithelium. "PCB 29-PQ 12 has been reported to exhibit pyroptotic activity in cervical cancer cells by activating caspase-1 and GSDMD." (PMID 39316325, 2025). "Tanshinone IIA can promote pyroptosis in cervical cancer HeLa cells and exert anticancer activity by regulating the mir-145/GSDMD signaling." (PMID 37864196, 2023). "However, tanshinone IIA 24 a furan-containing compound exhibits pyroptotic activity in cervical cancer cells by activating GSDMD." (PMID 39316325, 2025). "In conclusion, our study demonstrated that tanshinone II A may be regarded as a potential candidate for the treatment of cervical cancer by regulating miR-145/GSDMD signaling pathway." (PMID 32232409, 2020). "The results presented here provide evidence that modulation of miR-145/GSDMD is closely involved in the anticancer activity of tanshinone II A on HeLa cells, which provides a strong evidence to support that tanshinone II A can act as a potential anticancer drug against cervical cancer." (PMID 32232409, 2020).
dermatitis (6 papers, 2016 to 2025). An inflammatory process affecting the skin. "However, mice carrying GOF mutations in mouse Nlrp3 are protected from dermatitis when crossed onto a GSDMD-deficient background, implicating a pivotal role for GSDMD-mediated pyroptosis in the skin." (PMID 38649745, 2024). "Enhanced cleavage products of caspase-1, GSDMD, and IL-1β were observed in both imiquimod-induced psoriasis-like dermatitis (IIPLD) mouse epidermis and M5 (simulating psoriatic inflammatory challenge)-treated keratinocytes in vitro." (PMID 40332377, 2025). "highlighted a specific role of IL-1β, the downstream cytokine of NLRP3-GSDMD signaling, in provoking dermatitis in Sharpincpdm mice, suggesting that GSDMD may function as a potential checkpoint in CPD." (PMID 35774778, 2022).
epilepsy (6 papers, 2021 to 2025). A brain disorder characterized by episodes of abnormally increased neuronal discharge resulting in transient episodes of sensory or motor neurological dysfunction, or psychic dysfunction. "Moreover, pyroptosis is also closely related to epilepsy, however, it is unknown whether the core pyroptosis protein GSDMD is associated with the pathogenesis of epilepsy." (PMID 34421582, 2021). "The qRT-PCR results showed that the mRNA expression of GSDMD was significantly higher in the epilepsy group than in the sham group." (PMID 35095728, 2021). "Our study investigated the effect of agmatine on the core pyroptosis protein GSDMD in the context of epilepsy." (PMID 34421582, 2021). "We established a mouse model of kainic acid-induced epilepsy to verify the expression of GSDMD and GSDME at the transcriptome and protein levels." (PMID 35095728, 2021). "In our study, we found that GSDMD mRNA and protein expression was significantly upregulated after epilepsy, suggesting that GSDMD transcription is increased." (PMID 35095728, 2021). "At the same time, we established a mouse model of kainic acid-induced epilepsy to further confirm that the expression of GSDMD mRNA and protein after epilepsy was significantly higher than that of the sham group." (PMID 35095728, 2021). "In addition, we intend to apply more specific intervention techniques, such as siRNA and gene knockout to clearly identify the effect of GSDMD-mediated pyroptosis in epilepsy." (PMID 35153737, 2021). "We aimed to investigate the role of GSDMD in epilepsy and its mechanism." (PMID 34421582, 2021). "However, the role of GSDMD and its related mechanism in epilepsy remain to be elucidated." (PMID 34421582, 2021). "Therefore, we speculate that GSDMD staining in astrocytes may be related to the important role played by astrocytes in the pathophysiological mechanism of epilepsy." (PMID 35153737, 2021). "In a mouse model of pilocarpine-induced epilepsy, four studies consistently show that inflammation is enhanced through NLRP3, caspase 1, ASC, gasdermin D, IL-1β, and IL-18 pathways." (PMID 40217546, 2025). "Laboratory studies from epilepsy have shown that the levels of inflammasomes (NLRP1, NLRP3, caspase 1, IL-1β, ASC, AIM2, gasdermin D, IL-18, intracellular calcium ion, sTNFr2) were also elevated." (PMID 40217546, 2025). "We also conducted various experiments to validate the expression changes of three PANoptosis markers (ZBP1, GSDMD, and RIPK1) during the pathophysiological process of epilepsy." (PMID 38404827, 2024). "In this study, we then assessed the mRNA of ZBP1, GSDMD, and RIPK1 and the protein expression of ZBP1 and RIPK1 in epilepsy models in vitro." (PMID 38404827, 2024). "Our results confirmed changes in ZBP1, GSDMD, and RIPK1 expression during epilepsy onset, further supporting the potential involvement of PANoptosis in seizure pathogenesis." (PMID 38404827, 2024). "GSDMD and GSDME, the key executive molecules of pyroptosis, will help to understand the pathogenesis of epilepsy and aid in discovering new targets for anti-epileptic drug treatments." (PMID 35095728, 2021). "Additionally, we assessed the mRNA of ZBP1, GSDMD, and RIPK1 and the protein expression of ZBP1 and RIPK1 in epilepsy models in vitro." (PMID 38404827, 2024). "We observed a significant increase in the mRNA expression of ZBP1, GSDMD, and RIPK1 in the peripheral blood of newly diagnosed seizure patients compared to age-matched healthy children (P < 0.01), suggesting their involvement in epilepsy onset." (PMID 38404827, 2024). "However, it is worth noting that GSDMD and GSDME, as the executioner of pyroptosis, has not been studied in epilepsy thus far." (PMID 35095728, 2021).
esophageal squamous cell carcinoma (6 papers, 2019 to 2025). Esophageal squamous cell carcinoma (ESCC) is a type of esophageal carcinoma (EC) that can affect any part of the esophagus, but is usually located in the upper or middle third. "Metformin reduced cell viability by inducing pyroptosis caused by the cleavage of GSDMD in esophageal squamous cell carcinoma (ESCC) patients and human ESCC cell lines, including KYS510 and KYSE140." (PMID 33348858, 2020). "Metformin induces GSDMD mediated pyroptosis in esophageal squamous cell carcinoma cells by targeting the miR-497/Pelp1 axis." (PMID 41562058, 2025). "Metformin could induce GSDMD-mediated pyroptosis in esophageal squamous cell carcinoma (ESCC) by targeting the miR-497-PELP1 axis, indicating that pyroptosis-inducing reagents could serve as alternative treatments for chemo- and radiotherapy refractory ESCC." (PMID 34298833, 2021).
glaucoma (6 papers, 2021 to 2026). Increased pressure in the eyeball due to obstruction of the outflow of aqueous humor. "More importantly, studies in glaucoma and optic nerve injury models have similarly demonstrated GSDMD-mediated pyroptosis in RGCs." (PMID 41563626, 2026). "Notably, IHC showed that cGAS, STING, GSDMD, and Caspase-1 were significantly upregulated in the retinas of glaucoma patients." (PMID 37726272, 2023). "However, recent studies have implicated inflammasomes, caspase-1, and GSDMD in acute and chronic models of glaucoma, suggesting that apoptosis is not the only form of cell death involved in glaucomatous RGC loss." (PMID 35047535, 2021). "A few studies also supported targeting caspase-3/GSDME and caspase-8/GSDMD pathways in AMD and glaucoma." (PMID 35047535, 2021).
gout (6 papers, 2020 to 2025). A condition characterized by painful swelling of the joints, which is caused by deposition of urate crystals. "BRD4 plays a vital role in aggravating acute gouty arthritis by regulating NF-κB/NLRP3/gasdermin D (GSDMD) signaling pathway." (PMID 35154163, 2022). "In vitro experiments showed that MSU crystals rapidly increased the expression of GSDMD in mouse macrophages, providing evidence for the excessive occurrence of pyroptosis in gout patients." (PMID 36142364, 2022). "In conclusion, the role of pyroptosis in the pathogenesis of gout is still controversial, and whether GSDMD can be a target for the treatment of gout needs further investigation." (PMID 36142364, 2022). "Our current data demonstrated that BRD4 suppression could partially counteract the severity of pyroptotic death in acute gouty arthritis via the BRD4/NF-κB/NLRP3/GSDMD axis." (PMID 33162822, 2020). "In contrast, gout-associated uric acid crystals can activate NLRP3 inflammasome, resulting in GSDMD cleavage, IL-1β cytokine release, and the formation of membrane pores, suggesting that GSDMD may be actively involved in these diseases." (PMID 35774778, 2022).
heart failure (6 papers, 2022 to 2026). Inability of the heart to pump blood at an adequate rate to meet tissue metabolic requirements. "Another recent study on DOX-induced cardiotoxicity revealed that GSDMD can also be activated, causing pyroptosis, and that inhibiting GSDMD alleviated DOX-induced heart failure." (PMID 41550939, 2025). "GSDMD-induced pyroptosis plays a critical role in host defense and immune surveillance, as well as in conditions like sepsis, Alzheimer’s Disease, heart failure, and cancer." (PMID 39404370, 2024). "Recently, GSDMD has been shown to play important roles in the development of various inflammatory-related human diseases including heart failure and cancer, suggesting that it is a promising therapeutic target for these diseases." (PMID 39404370, 2024). "This suggests that the timing of interventional strategies for targeting GSDMD as well as the degree of neutrophil inhibition are critical in preventing postinfarction heart failure." (PMID 34752417, 2022). "Our study provides mechanistic insights into molecular regulation of neutrophil generation and mobilization after AMI, and supports GSDMD as a new target for improved ventricular remodeling and reduced heart failure after AMI." (PMID 34752417, 2022). "We anticipate that our studies may be broadly applicable to cardioprotective therapy, specifically targeting GSDMD and neutrophil production for improved ventricular remodeling and reduced heart failure after AMI." (PMID 34752417, 2022). "Furthermore, in rats with ISO-induced heart failure, pyroptosis and inflammatory responses were exacerbated, including increases in GSDMD, cleaved GSDMD, caspase 1, cleaved caspase 1, and IL-1β by 1.56- (P<0.05), 2.87- (P<0.001), 2.14- (P<0.01), 2.67- (P<0.01), and 7.11-fold (P<0.001), respectively." (PMID 36327230, 2022). "Based on our findings from the murine AMI models, GSDMD inhibition (within hours of AMI) may be a novel therapy to reduce scar formation and prevent heart failure after AMI." (PMID 34752417, 2022).